RNA5S16 (RNA, 5S ribosomal 16)
Synonyms: RN5S16
Gene: Ribosomal RNA gene on chromosome 1 (228,643,809 to 228,643,927, reverse strand). Ensembl gene ENSG00000202257.
Gene Ontology:
Molecular function: structural constituent of ribosome
Cellular component: ribosome
Homologues: Orthologues: dog 5S_rRNA (100% identical), guinea pig 5S_rRNA (100% identical), macaque 5S_rRNA (100% identical), mouse Gm22291 (100% identical), mouse n-R5s123 (100% identical), mouse n-R5s138 (100% identical), mouse n-R5s149 (100% identical), pig 5S_rRNA (100% identical), rabbit 5S_rRNA (100% identical), rat 5S_rRNA (100% identical), macaque 5S_rRNA (99% identical). Paralogues in human: RNA5S1 (100% identical), RNA5S10 (100% identical), RNA5S11 (100% identical), RNA5S12 (100% identical), RNA5S13 (100% identical), RNA5S14 (100% identical), RNA5S15 (100% identical), RNA5S17 (100% identical), RNA5S2 (100% identical), RNA5S3 (100% identical), RNA5S4 (100% identical), RNA5S5 (100% identical), and 26 more.